EGFR (epidermal growth factor receptor)
Diseases named in the same sentence as EGFR in open-access papers (continued):
Sharing a sentence is not in itself a finding about the gene and the disease.
glioma (continued). "Moreover, bradykinin is also known to interact with EGFR and stimulate downstream signaling pathways to enhance cell invasion as well as promote angiogenesis through elevated VEGF expression in glioma." (PMID 33585190, 2020). "Moreover, a recent screening performed in fly glioma models had allowed us to identify Kish, the Drosophila TMEM167A orthologue, as a key modulator of EGFR trafficking/recycling during glioma development." (PMID 31947645, 2020). "LncRNA HOXA-AS2 regulated malignant glioma behaviors via the RND3 expression and miR-373/EGFR axis." (PMID 33178271, 2020). "Finally, Go and KEGG analysis revealed WNT5A was associated with multiple signal translations, and crucial oncogenes (EGFR and MDM2) and 2 important tumor suppressors (PTEN and IKN4a/ARF) were found closely correlated with WNT5A in glioma." (PMID 32181818, 2020). "Intracranial xenograft models further elucidated that BIP-MPC-NP enhanced TMZ chemosensitivity via attenuating the EGFR and MET signaling pathways, including phosphorylation of p38 and reducing E2F1 expression accompanied by elevated TTP in TMZ-resistant gliomas." (PMID 32001707, 2020). "In the present study, SEL1L overexpression associates significantly with TERT promoter mutation, EGFR gene amplification, LOH on 10q and (borderline) 9p chromosomes, all well‐known negative prognostic markers for gliomas." (PMID 31111685, 2020). "Although we have previously observed that the growth of most of the lines used in this study is EGFR-dependent, we cannot discard that TMEM167A might be necessary for the trafficking and/or the signaling of other receptors present in gliomas." (PMID 31947645, 2020). "Inhibiting EGFR and HER-2 simultaneously using a liposomal formulation of lapatinib resulted in enhanced amino-levulinic acid-PDT efficacies and prolonged survival in an orthotopic rat model of glioma." (PMID 32485915, 2020). "Furthermore, L1CAM function in GBM cell migration was determined by the same group; ADAM10 would cleavage L1CAM ectodomain, which then would activate EGFR and integrins (FAK-mediated process) to promote glioma CSC migration." (PMID 33177991, 2020). "“INPUT” results confirmed Ninj2, EGFR, PDGFRβ and FGFR expression in the glioma cells." (PMID 31794427, 2019). "Moreover, those gliomas exhibited significantly increased copy number alterations including recurrent focal amplifications of PDGFA and EGFR, as well as recurrent deletions of CDKN2A/B." (PMID 31428092, 2019). "The amplification and activation of EGFR, platelet derived growth factor receptor α (PDGFRα), and mesenchymal-epithelial transition factor (MET) promote the proliferation and invasion of glioma cells and are correlated with recurrence and therapeutic resistance." (PMID 31245283, 2019). "The amplification and activation of EGFR, platelet derived growth factor receptor α (PDGFRα), and mesenchymal-epithelial transition factor (MET) are the top three desregulated RTKs, which promote the proliferation and invasion of glioma cells." (PMID 31221203, 2019). "“INPUT” results confirmed Ninj2, EGFR, PDGFRβ and FGFR expression in the glioma tissues." (PMID 31794427, 2019). "Parallel immunofluorescence analysis confirmed that teratomas regionally expressed EGFR, but never CD19, while the glial tumors retained uniform EGFR and CD19 surface expression." (PMID 31903167, 2019). "FBS stimulation of C6 glioma cells led to phosphorylation of MET, EGFR, AKT, and ERK1/2." (PMID 31595389, 2019). "Consistent with existing literature, we found EGFR and PDGFR to be upregulated in gliomas." (PMID 30909495, 2019). "However, the key immunosuppressive factor CTLA-4 was confirmed elevated in EGFR-MUT cases, which indicating a possible existence of Treg cells in lower-grade glioma context." (PMID 31801484, 2019).
glioma (continued). "Only six pathways are enriched and include EGFR signaling and Glioma pathways which does not allow any further analysis to compare the patients and group them." (PMID 31527881, 2019). "Several investigations also revealed that the interaction of EGFR and IGF1R may result in resistance to EGFR-TKIs in glioma and breast and prostate cancers." (PMID 30823937, 2019). "CHIP could function as a tumor suppressor by regulating and degrading epidermal growth factor receptor (EGFR) in pancreatic cancer, RelA in gastrointestinal cancer, and c-Myc in glioma." (PMID 31130821, 2019). "In addition, the clinical data were also analyzed to assess the prognostic value of the combination of EGFR and VEGR genes, showing their clinical relevance in glioma patients." (PMID 31074391, 2019). "In this work, we reported for the first-time that EGFR amplification had no significant prognostic value in molecular subgroups of gliomas - IDH-wildtype GBM and astrocytomas." (PMID 31623593, 2019). "LRIG1 regulates EGFR, and its soluble form has been shown to inhibit in vivo glioma growth irrespective of EGFR status." (PMID 31842352, 2019). "Our current study presents a new hypothesis wherein neuron-type NHE5 ectopically expressed in C6 glioma cells plays a critical role in MET, EGFR, and integrin signaling in glioma." (PMID 31595389, 2019). "For instance, changes (e.g., mutation and methylation) in the serum DNAs (ctDNAs), such as MGMT 7-9, EGFR 10, and PTEN 9, have been proven to be effective biomarkers of glioma and may have the potential for the diagnosis of glioma." (PMID 31410219, 2019). "In a study on the effects of radiotherapy on gliomas, Park found that radiation switched on the EGFR-mediated p38/Akt and PI3K/Akt signaling pathways, which led to increased glioma cell metastasis and invasive ability by up-regulating matrix metalloproteinase 2 (MMP-2) expressions." (PMID 29958545, 2018). "The oncogenes EGFR and c-MET were co-expressed in approximately 41% of these gliomas." (PMID 29621254, 2018). "The preparation and application of Fe3O4@Au composite MNPs have been reported before the present study, but the research of it used as a carrier to fix commercially available EGFR McAb-C225 for anti-glioma has not been conducted before." (PMID 29652919, 2018). "This interesting finding might provide insight into the molecular mechanism of why gliomas with EGFR amplification and PTEN deletion are resistant to anti-EGFR therapy." (PMID 30595797, 2018). "Alterations in PI3K, EGFR, and PTEN are less frequent in pediatric than in adult gliomas." (PMID 29805974, 2018). "Combined with the observation from previous studies that EGFR mutations are rarely to never found in pediatric HGG and DIPG, these data suggest that the role of EGFR signaling in pediatric gliomas is more limited than in the adult counterpart." (PMID 29164272, 2018). "A recent study demonstrated that HB-EGF drives glioma tumorgenesis in mice lacking Ink4a/Arf and Pten through EGFR signaling." (PMID 29864158, 2018). "Moreover, EGFR, phosphorylated STAT3, CD133 and Nestin expression was reduced in xenografted glioma tissues in response to honokiol treatment, which was consistent with in vitro results we observed." (PMID 30587839, 2018). "Activated EGFR increased the production of tumor‐derived VEGF that acts on endothelial cells in a paracrine manner to promote angiogenesis and amplification of EGFR also indicated poor prognosis in glioma." (PMID 30216655, 2018).
glioma (continued). "EGFR signaling is known to promote many components of a more aggressive tumor phenotype and P-PRAS40 has been reported as an independent prognostic marker with regard to time to progression in a small glioma cohort." (PMID 30129426, 2018). "It remains unresolved why EGFR targeting has not been successful for glioma as it should be ideally suitable in the context of this disease." (PMID 30619758, 2018). "Since miR‐19 might negatively regulate EGFR via LRIG1, the impact of EGFR on invasion and angiogenesis of glioma cell may be connected with miR‐19." (PMID 30073755, 2018). "Moreover, other EGFR inhibitors like temozolomide, lomustine, erlotinib, and gefitinib, are approved by the FDA for the treatment of glioma." (PMID 28630865, 2017). "In glioma, an EGFR mutant lacking exons 2–7, corresponding to the EGFR extracellular domain, has been identified." (PMID 29140271, 2017). "We have shown that CSCs were significantly more resistant to chemotherapy and radiation than non-CSCs, and that inhibition of EGFR, by gefitinib, can sensitise both human and canine glioma CSCs to the cytotoxic effects of doxorubicin and radiation." (PMID 29069805, 2017). "In this review, we focused on the impact of EGFR and EGFRvIII on the upregulation of ECM-degrading proteases and the activation of signaling pathways responsible for increased glioma cell invasion and angiogenesis and the subsequent possibilities to develop effective combined gene therapy." (PMID 28629170, 2017). "Several compounds targeting EGFR or CHK1 are already in clinical use and our study suggest that combining these compounds with stereotactic HFRT for recurrent high grade gliomas might be of particular interest." (PMID 28754127, 2017). "HKI-272 is an EGFR and HER2 inhibitor that demonstrated anti-tumor activity in glioma models." (PMID 27611946, 2017). "Moreover, the expression of some key factors in gliomas were detected by QPCR, such as IDH1, TERT, EGFR, PTEN, ATRX." (PMID 28199986, 2017). "In glioma, EGF or substance P can activate EGFR, which activates ERK and EGR1 biosynthesis." (PMID 29246166, 2017). "When a copy number of ≥4 of the indicated genes was considered as CNG (or gene amplification), we found that EGFR CNG in 62/127 (48.8%) gliomas, HER2 in 44/127 (34.6%) gliomas, HER3 in 47/127 (37.0%) gliomas, and HER4 in 50/127 (39.4%) gliomas, whereas none was found in control subjects." (PMID 29190914, 2017). "On the other hand, most, if not all, gliomas with EGFR amplifications showed strong positive correlation with our NAMPT-derived signature." (PMID 29245920, 2017). "These tumor responses motivated our investigation of the effects from genetic as well as pharmacologic inhibition of Axl and EGFR, either concurrent with the PLX4720 tool compound treatment or subsequent to BRAFV600E glioma adaptation to tool compound treatment." (PMID 27611946, 2017). "It ultimately limits the success of therapies such as monoclonal antibody-bases therapies, EGFR- and EGFRvIII-specific small molecule inhibitors, or vaccines, because it is not possible to address all single glioma cells with only one specific treatment." (PMID 28629170, 2017). "It has been reported that glioma growth, invasion, and angiogenesis signals are related to ECM components such as collagen, laminin, and integrin, and to receptor tyrosine kinase (RTK) genes such as EGFR, PDGFR, IGF1R, and Met." (PMID 29161257, 2017). "Furthermore, many microRNAs regulate glioma radioresistance through acting with AKT signaling proteins, including EGFR, GSK3, Bmi." (PMID 29246031, 2017). "Src increases EGFR-mediated pathway activity in many cancer types and can be activated via FAK-binding which initiates a crosstalk between integrin-FAK signaling and other pathways involved in glioma invasion." (PMID 28629170, 2017).
glioma (continued). "Several compounds targeting EGFR or CHK1 are already in clinical use and combining them with stereotactic hypofractionated radiotherapy for recurrent high grade gliomas might be of particular interest." (PMID 28754127, 2017). "EGFR is known as a key RTK and leading therapeutic target in many cancers including gliomas." (PMID 27811356, 2016). "Copy number analysis of the 100 K SNP data in the REMBRANDT dataset detected only low-level amplification of EGFR in both subsets of PM gliomas and almost no PM gliomas in GSE16011 harbored EGFR amplification." (PMID 27385209, 2016). "Compared with those RMPAhigh gliomas without EGFR alterations, RMPAhigh gliomas with EGFR alterations showed higher EGFR expression." (PMID 27385209, 2016). "We have previously shown that human BRAFV600E glioma but not melanoma cell lines express high levels of EGFR." (PMID 27713119, 2016). "EGFR has been shown to support tumorigenicity primarily through signaling toward downstream targets including RAS/RAF/MAPK and PI3-K/AKT pathways, which in turn leads to increased proliferation, angiogenesis, migration and invasion of glioma cells." (PMID 27043632, 2016). "As opposed to the “all gliomas” group, EGFR was overexpressed in all tumors (100%) of IDH-mutant 1p/19q co-deleted ATRX-wt WHO grade-II regardless of the rs55705857 genotype." (PMID 27282637, 2016). "This demonstrates the important point that alternative mechanisms, which are independent of alterations in EGFR, can contribute to the RMPAhigh signature in those gliomas." (PMID 27385209, 2016). "Cell cycle progression in human glioma U87MG and U251 cells was halted at S/G2/M phase via the Wnt/β-catenin signaling pathway and related genes such as PRR11, Cyclin A, p-CDK2, VEGFR-1/2, p-VEGFR-1/2 and EGFR." (PMID 27613831, 2016). "As was recently demonstrated, elevated expression of EGFR or phospho-EGFR, such as that observed in U87ΔEGFR glioma tumors, does not guarantee enhanced uptake of [11C]erlotinib." (PMID 25853010, 2015). "In comparison to IDHmut gliomas, IDHwt gliomas have greater activation of receptor tyrosine kinase signaling through EGFR gain, MET gain, and BRAF gain, in addition to increased gains in cell cycle activators and losses of cell cycle inhibitors compared to IDHmut gliomas." (PMID 26091668, 2015). "In glioma cells multiple signaling pathways, including those involving MAPK and PI3K/Akt, are simultaneously activated by BRAFV600E inhibitor induced feedback activation of EGFR." (PMID 26023796, 2015). "Taken together, the data showed that combined treatment is effective regardless of the EGFR status in human glioma." (PMID 25886314, 2015). "This pattern of large CNAs in IDHwt gliomas contrasts with IDHmut gliomas, in which changes on chromosomes 7 and 10 were either absent or more focal around the EGFR, MGMT, and/or PTEN genes (Arrows)." (PMID 26091668, 2015). "Despite the fact that combination of EGFR targeting drugs and rapamycin has been used before, the effect of mono-treatment of Nimotuzumab, rapamycin and combination therapy in human glioma expressing different types of EGFR is not well-studied." (PMID 25886314, 2015). "In spite U87MG glioma cells are not mutant for EGFR, they constitutively activate MAP kinase pathway in virtue of mutations affecting Focal Adhesion Kinases and GRP3." (PMID 25576921, 2015). "Anti-EGFR function of EFEMP1 had on the expression of EGFR and glioma patient prognosis." (PMID 25987128, 2015). "However, only IDHmut grade IV gliomas were enriched for alterations in pathways involving regulation of actin cytoskeleton, RAS, and EGFR." (PMID 26091668, 2015). "EGFR triggered the extracellular signal-regulated kinase (ERK)-mitogenic activated protein kinase (ERK/MAPK) signaling in many cells lines, an important component of radiation-induced hormesis and glioma radio-resistance." (PMID 25749386, 2015).
glioma (continued). "However, decreased miR-145 expression promoted U87 glioma cell proliferation, invasion and angiogenesis, and reduced-expression of miR-145 increased ADAM17 and EGFR expression in U87 cells." (PMID 25544346, 2015). "Though the number of EGFR amplified grade II gliomas was small (n = 6), it's worthwhile to note that this small subset of grade II tumors exhibited worse prognosis than EGFR non-amplified grade III gliomas (p = 0.006)." (PMID 26369702, 2015). "It is therefore interesting and significant that combining EGFR and BRAFV600E therapies may prove an effective anti-glioma strategy." (PMID 26023796, 2015). "Furthermore, low expression of miR-145 in glioma cells was correlated to increased ADAM17 and EGFR expression." (PMID 25544346, 2015). "Our study suggests that EGFR and BRAFV600E combination therapy might be worth investigating in clinical trial on BRAFV600E glioma, which thus far has poor clinical prognosis under standard radiation and chemotherapeutic regimens." (PMID 26023796, 2015). "Aberrant phosphotyrosine-based signaling is a hallmark of cancer, and gliomas are no exception; tyrosine kinase membrane receptors like EGFR, ERBB2, PDGFRA, MET and VEGFR2 have been implicated in glioma growth, angiogenesis and cell motility." (PMID 25238264, 2014). "It suggests an oncogenic role of EFEMP1 in gliomas that do not have high EGFR expression, or where tumor growth was not largely driven by EGFR-activated signaling." (PMID 25594013, 2014). "First, we evaluated p-EGFR, MGMT expression levels in a panel of glioma cell lines." (PMID 24418474, 2014). "In addition to the EGFR signaling axis, PDGFRα and its ligands, PDGF-A and PDGF-B, are represented in gliomas, especially in HGG." (PMID 25147764, 2014). "Our data provide evidence that the PI3K/mTOR/S6 signaling pathway can be activated through expression of EGFR/PI3K p110α rather than through reduced expression of PTEN in glioma." (PMID 24718026, 2014). "EGFR overexpression and activation is considered an etiological factor in several types of cancer, such as head and neck squamous cell cancer, non-small cell lung cancer (NSCLC), colorectal cancer, breast cancer and some tumors of the central nervous system." (PMID 24709958, 2014). "In addition, marked EGFR staining, ++ or +++, was observed in 40, 78.4 and 90.3% of grade II, III and IV immunopositive gliomas, respectively." (PMID 23946790, 2013). "Perhaps even more disappointingly, clinical studies evaluating combinations of mTOR and EGFR inhibitors in patients with recurrent glioma demonstrated limited responses and these were not sustained." (PMID 23555046, 2013). "The overexpression of EGFR could rescue the inhibitory effect of miR-219-5p on MAPK/PI3K pathways and also on glioma cell migration." (PMID 23690991, 2013). "For instance, the hypermethylation status of the epidermal growth factor receptor (EGFR) and methyl-guanine-DNA methyltransferase (MGMT) could play a role in glioma progression." (PMID 23902708, 2013). "Moreover, PTPRK mutations altered the inhibitory effect of wild type PTPRK on EGFR and β-catenin signaling pathways which correlate with observed alterations in PTPRK mediated suppressive effects on growth and migration of glioma cells." (PMID 23696788, 2013). "Taken together with reduced p-Erk expression, miR-145 transfection may decrease glioma cell migration and invasion through ADAM17/EGFR/ERK signaling pathway." (PMID 23076445, 2013).